ADAM9 (ADAM metallopeptidase domain 9)
Diseases named in the same sentence as ADAM9 in open-access papers (continued):
Sharing a sentence is not in itself a finding about the gene and the disease.
gastric cancer (18 papers, 2008 to 2025). A primary or metastatic malignant neoplasm involving the stomach. "In an animal model of gastric cancer, miR-129-5p suppressed ADAM9 protein expression and tumor growth." (PMID 39755747, 2025). "ADAM9, which is ubiquitously expressed in human tissues, is highly expressed in several types of cancer, such as lung, breast, renal, and gastric cancers (52, –, 55)." (PMID 37713503, 2023). "The lncRNA LINC00689 causes miR-526b-3p to sponge and leads to the upregulation of ADAM9 to promote the progression of gastric cancer." (PMID 34101736, 2021). "Blocking of ADAM9 activity with specific antibodies resulted in inhibited cell growth of gastric cancer cell lines." (PMID 25177692, 2014). "Functionally, blocking of ADAM9 with specific antibodies resulted in inhibited cell growth of gastric cancer cell lines." (PMID 18582378, 2008). "In addition to regulating the occurrence of gastric cancer, ADAM9 protein also plays an important role in promoting intra-abdominal metastasis and diffusion." (PMID 32875951, 2020). "ADAM9 is negatively regulated by miR-129-5p and suppresses the progression of gastric cancer." (PMID 33146718, 2020). "It increases the expression and activity of ADAM9 and increases the invasion of the tumor, which may help the growth and spread of gastric cancer." (PMID 32875951, 2020). "In addition, RAV-18, an ADAM9-specific blocking antibody, showed in vivo antitumor activity in a gastric cancer xenograft model." (PMID 29118335, 2017). "ADAM9 has been previously implicated as a potential oncogene and therapeutic target for various cancers whilst MGAM gene has been reported to be amplified in gastric cancer genomes." (PMID 23405089, 2013). "Gastric cancer tissues (n = 415) expressed significantly higher mRNA levels of ADAM8, ADAM9, ADAM10, ADAM12, and ADAM17 (p < 0.001) than normal tissues (n = 35)." (PMID 39755747, 2025). "When gastric cancer tissue was paired with normal tissue from the same patient with gastric cancer (n = 32), ADAM8, ADAM9, ADAM10, ADAM12, and ADAM17 mRNAs showed significantly higher expression in gastric cancer tissues (p < 0.05)." (PMID 39755747, 2025). "Deregulation of protein expression, such as FN1 and ADAM9 (upregulated) or SPARCL-1 (downregulated), has been shown to affect cell growth and tissue proliferation in gastric cancer." (PMID 36672527, 2022). "As a proof-of-concept pilot study, the expression of ADAM8, ADAM9, ADAM10, ADAM12, ADAM17, and major histocompatibility complex (MHC) class I chain-related sequence A (MICA), a ligand for NKG2D, in gastric cancer was investigated in silico using The Cancer Genome Atlas (TCGA) database." (PMID 39755747, 2025). "When ADAM9 was knocked out or the specific targeting monoclonal antibody (RAV-18) was used, gastric cancer cell proliferation and invasion could be inhibited in cells that were originally at high levels of ADAM9 expression." (PMID 32875951, 2020). "A role for HULC in the regulation of EMT has been observed in HCC where it functions as a ceRNA for miRNAs (miR-122, miR-200a-3p, miR-372, and miR-488) to mediate EMT via upregulation of Snail, ZEB1, or ADAM9, and this lncRNA has also been reported to induce EMT in gastric cancer." (PMID 29701689, 2018).
hepatocellular carcinoma (16 papers, 2004 to 2025). A malignant tumor that arises from hepatocytes. "This is consistent with the observation that decreased ADAM9 mRNA expression correlated with a better response to nivolumab therapy in hepatocellular cancer." (PMID 38469304, 2024). "ADAM9 knockdown experiments have revealed that ADAM9 is involved in MICA ectodomain shedding of human hepatocellular carcinoma (HCC) cells before." (PMID 35740916, 2022). "Recently, we discovered that regorafenib upregulates mMICA to a greater extent than sorafenib, suppressing ADAM9 in hepatoma cells, confirming the role of ADAM9 as an immunotherapeutic target." (PMID 32683508, 2021). "In vitro, this molecule presents interesting off-target effects on ADAM9 expression as evidenced by a recent study on the human hepatocellular carcinoma cell line HepG2." (PMID 24715892, 2014). "For example, miR-203 could suppress the proliferation and metastasis of hepatocellular carcinoma by targeting ADAM9." (PMID 29743816, 2018). "ADAM9 overexpression was also demonstrated in prostate, breast and liver cell carcinomas." (PMID 14997207, 2004). "Sorafenib, a multi-receptor tyrosine kinase inhibitor used clinically for hepatocellular carcinoma (HCC), has been reported to decrease ADAM9 mRNA and protein levels." (PMID 40427200, 2025). "The chemotherapeutics sorafenib and regorafenib inhibit shedding of MHC class I-related chain A (MICA) from hepatocellular carcinoma (HCC) cells by suppressing a disintegrin and metalloprotease 9 (ADAM9)." (PMID 32245188, 2020). "During this process and the invasion stage of hepatocellular carcinoma, ADAM9 promotes the invasion of HCC by degrading the basement membrane components including laminin-1." (PMID 32875951, 2020). "In addition, ADAM9 inhibition increases the expression of membrane-bound MICA on the tumor cell, enhancing the NK sensitivity of hepatocellular carcinoma cells." (PMID 24715892, 2014). "It is noteworthy to speculate whether some proteases including MMP-3, ADAM9 and MT1-MMP are activated in thyroid carcinoma as well as in hepatoma and ovarian carcinoma." (PMID 23917679, 2013).
non-small cell lung carcinoma (8 papers, 2014 to 2024). A group of at least three distinct histological types of lung cancer, including non-small cell squamous cell carcinoma, adenocarcinoma, and large cell carcinoma. "Importantly, a recent study showed that high ADAM9 expression was an independent factor linked with shortened survival and has been proposed to serve as a predictive biomarker for the selection of non-small cell lung cancer patients eligible for postoperative adjuvant chemotherapy treatment." (PMID 27571068, 2016). "The high expression of ADAM9 gene in patients with non-small cell lung cancer is closely related to targeted brain metastases." (PMID 32875951, 2020). "Additionally, an elevated ADAM9 expression level was also found in liver metastases from colon carcinomas and brain metastases from non-small cell lung cancer." (PMID 27571068, 2016).
renal cell carcinoma (8 papers, 2008 to 2024). "For instance, ADAM9 protein expression has been shown to significantly associate with poor patient survival in ductal adenocarcinoma and renal cell cancer patients." (PMID 27571068, 2016). "We evaluated the ADAM9 expression on protein and transcript level to clarify a diagnostic or prognostic value of ADAM9 in renal cell cancer." (PMID 18582378, 2008). "This correlation was also observed in pancreatic ductal adenocarcinomas and renal cell cancer that higher ADAM9 expression is related to poorer tumor differentiation and patient's prognosis." (PMID 32637415, 2020). "Upregulation of ADAM9 expression was found to be correlated with poorer patient survival in renal cell cancer." (PMID 32637415, 2020). "On the other hand, only 4% of normal tissues showed a strong ADAM9 protein expression in comparison to 34% of the tumours, which clearly supports the notion that ADAM9 is up-regulated on protein level in a larger proportion of renal cell carcinomas." (PMID 18582378, 2008). "This is an important observation for it allows the use of TMAs for evaluation of ADAM9 in renal cell cancer." (PMID 18582378, 2008). "ADAM9 is strongly expressed in a large proportion of renal cell cancers, concordant with findings in other tumour entities." (PMID 18582378, 2008). "Our results are in line with this notion and demonstrate a prognostic value of ADAM9 for renal cell cancer at least in the univariate analysis." (PMID 18582378, 2008). "We evaluated the expression of ADAM9 on protein and transcript level in a clinico-pathologically characterized renal cell cancer cohort." (PMID 18582378, 2008). "The findings from the survival analysis in this study are not consistent with those in renal cell carcinoma and lung adenocarcinoma and may again verify the non-existence of the ADAM9/CDCP1/t-PA pathway in OSCC." (PMID 39441449, 2024). "Fisetin inhibited the migration as well as the invasion of human renal cell carcinoma (RCC) cells via the downregulation of CTSS and MMP-9 (ADAM9) and disintegrin." (PMID 36558146, 2022).
lung adenocarcinoma (7 papers, 2014 to 2026). A carcinoma that arises from the lung and is characterized by the presence of malignant glandular epithelial cells. "Based on these results, we proposed a working model for an ADAM9-miR-218-CDH2 signaling pathway in aggressive lung adenocarcinoma cells." (PMID 24705471, 2014). "This study revealed that ADAM9 activates CDH2 through the release of miR-218 inhibition on CDH2 in lung adenocarcinoma." (PMID 24705471, 2014). "To understand whether the expression of ADAM9 and CDH2 were correlated with the malignancy of lung adenocarcinoma, we detected the endogenous expression levels of ADAM9 and CDH2 using real-time PCR and western blot analyses." (PMID 24705471, 2014). "Moreover, a significant positive correlation of ADAM9 and CDCP1 expression was detected in lung adenocarcinoma patients from The Cancer Genome Atlas (TCGA) dataset (R = 0.377)." (PMID 28537886, 2017). "We further demonstrated that ADAM9 could inhibit the expression of miR-218 and its precursor pri-miR-218-1 and could, in turn, up-regulate the expression of CDH2 to increase the mobility of lung adenocarcinoma cells." (PMID 24705471, 2014).
pancreatic ductal adenocarcinoma (7 papers, 2004 to 2023). An infiltrating adenocarcinoma that arises from the epithelial cells of the pancreas. "In pancreatic ductal adenocarcinoma, ADAM9 knockdown cells had increased expression levels of E-cadherin compared with controls." (PMID 35740916, 2022). "ADAM9 is highly expressed in pancreatic ductal adenocarcinoma and is closely related to vascular invasion of cancer cells." (PMID 32536819, 2020). "A disintegrin and a metalloprotease (ADAM)‐9 is a metzincin cell‐surface protease with strongly elevated expression in solid tumors, including pancreatic ductal adenocarcinoma (PDAC)." (PMID 30556643, 2019). "Gene expression profiling revealed ADAM9 to be distinctly overexpressed in pancreatic ductal adenocarcinoma (PDAC)." (PMID 14997207, 2004). "Pancreatic ductal adenocarcinomas showing cytoplasmic ADAM9 expression correlated with poor tumour differentiation and also with shorter overall survival than in cases showing only an apical membranous staining pattern (P=0.001)." (PMID 14997207, 2004).
colon carcinoma (6 papers, 2014 to 2021). "In patients with colon cancer, ADAM9 was found to co-localize with cadherin E, suggesting that it may be more involved in E-cadherin-mediated cancer cell invasion in colon cancer cells." (PMID 32875951, 2020). "Overexpression of ADAM9 promotes colon cancer cells invasion." (PMID 25594007, 2014). "H3K36me2, expressions of multiple oncogenes (ADAM9, EGFR, Sox2, Bcl-2, SYK, and MET) and Akt activation were significantly decreased after NSD2 silencing or knockout in primary colon cancer cells." (PMID 34671018, 2021).
cone-rod dystrophy (6 papers, 2008 to 2018). Inherited retinal dystrophies that belong to the group of pigmentary retinopathies. "In case 3, we identified one predicted-pathogenic variant in ADAM9 (p.Gln800His), associated with cone-rod dystrophy 9 [MIM #612775]." (PMID 30116628, 2018). "ADAM-9 null mutations were found in patients from families with recessively inherited cone-rod dystrophy (CRD), an inherited progressive retinal dystrophy." (PMID 27120619, 2016). "Evaluation of genes in this region suggested A Disintegrin And Metalloprotease domain, family member 9 (ADAM9), identified concurrently elsewhere as the cause of human cone-rod dystrophy 9 (CORD9), as a strong positional candidate for canine crd3." (PMID 20806078, 2010).
liver cancer (6 papers, 2014 to 2024). An epithelial or non-epithelial malignant neoplasm that arises from the liver. "Immunohistochemical and western blot analyses confirmed that ADAM9 is upregulated in human liver cancer cells, and ADAM9 causes reactive oxygen species (ROS) generation through the interaction with NADPH oxidase, promoting the liver cancer cell metastasis and epithelial–mesenchymal transition (EMT)." (PMID 34528498, 2021). "We found that upon knockdown of several ligands (VEGFA, ITGB3BP and ADAM9) in M2 macrophages, there was significant reduction in at least one of the liver cancer stem cell markers tested." (PMID 38169544, 2024). "Taken together, our study first illustrates the influence of ADAM9 on liver cancer cell radiosensitivity." (PMID 34528498, 2021). "ADAM9 has also been reported to be overexpressed in the cancer microenvironment of several cancer types, including liver cancer." (PMID 32683508, 2021). "Our study corroborates these findings, as we identified abnormal overexpression of ADAM9, ADAM10, ADAM15, and ADAM17 in liver cancer tissues through both GEPIA website analysis and PCR experiments." (PMID 39346916, 2024). "The results confirmed that ADAM9, ADAM10, ADAM15, and ADAM17 exhibited an upregulation trend in at least one liver cancer cell line, consistent with our earlier predictions." (PMID 39346916, 2024). "Prior research has documented a noteworthy upregulation of ADAM family members, particularly ADAM9, ADAM10, and ADAM17, in liver cancer, indicating a close link with tumor advancement." (PMID 39346916, 2024). "ADAM9 decreased HCC radiosensitivity by regulating autophagy, which provides a new target for enhancing the curative effect of liver cancer radiotherapy." (PMID 34528498, 2021). "In addition to the ADAM10 gene, ADAM9 and ADAM17 are the other frequently reported genes in liver cancer, playing a crucial regulatory role in chemotherapy resistance and malignant tumor progression." (PMID 39346916, 2024).
oral squamous cell carcinoma (6 papers, 2013 to 2025). "We, therefore, analyzed the expression of kallikrein 5, cathepsin Vand ADAM9 in oral squamous cell carcinoma cell lines, HSC-4 and SCC-25, as well as the oral adenocarcinoma cell lineACC-2, by western blot and immunofluorescence." (PMID 30602733, 2019). "Low expression of miR-126-5p in oral squamous cell carcinoma has also been observed by others, with evidence of negative regulation of tumorigenesis via targeting of KRAS, as well as migration and invasion of cancer cells via downregulation of ADAM9." (PMID 34439138, 2021).
ovarian carcinoma (6 papers, 2012 to 2020). A malignant neoplasm originating from the surface ovarian epithelium. "The oncogene a disintegrin and metalloproteinase 9 (ADAM9) was up‐regulated in ovarian cancer tissues, and the present study aims to explore the potential diagnostic and prognostic value of ADAM9 in ovarian cancer (OC)." (PMID 31793719, 2020). "(2018) showed that ADAM9 suppresses cisplatin‐induced apoptosis in ovarian cancer cell lines, a phenotype abrogated in ADAM9 knockdown cells." (PMID 30556643, 2019). "Unlike AsPC‐1 and MiaPaCa‐2 cells, ADAM9 appears to counteract the motility of Panc‐1 cells, similar to the situation observed in ovarian carcinoma cells." (PMID 30556643, 2019).
thyroid cancer (6 papers, 2013 to 2022). "More importantly, knockdown of ADAM9 reversed the neutralization effect of miR-182-5p on the RUNDC3A-AS1 knockdown-induced inhibition of thyroid cancer cell migration and invasion." (PMID 34046406, 2021). "Mechanistically, the effect of RUNDC3A-AS1 on the thyroid cancer was partially mediated by miR-182-5p/ADAM9 axis." (PMID 34046406, 2021). "RUNDC3A-AS1 inhibited the expression of miR-182-5p to increase the expression level of ADAM9, thus further aggravating the malignancy of thyroid cancer." (PMID 34046406, 2021). "Knockdown of RUNDC3A-AS1 decreased cell migration and invasion of thyroid cancer and alleviated tumor metastasis to lung through regulation of miR-182-5p/ADAM9 axis." (PMID 34046406, 2021). "Taken together, RUNDC3A-AS1 regulates thyroid cancer cell migration and invasion through miR-182-5p/ADAM9 axis." (PMID 34046406, 2021). "RT-qPCR analysis indicated that the expression level of ADAM9 was markedly increased in thyroid cancer tissues and thyroid cancer cell lines." (PMID 34046406, 2021). "ADAM9 was considered to be a potential target of miR-182-5p in thyroid cancer because it played an important role in tumor migration, invasion and metastasis." (PMID 34046406, 2021). "The results suggested that the expression levels of RUNDC3A-AS1 in thyroid cancer tissues and cell lines were positively correlated with ADAM9 expression, while the expression levels of miR-182-5p were negatively correlated with ADAM9 expression." (PMID 34046406, 2021). "In the present study, we show overexpression of miR-126-3p significantly inhibits thyroid cancer cell migration and metastasis, and that the protein expression level of ADAM9 is reduced in thyroid cancer cell lines in which miR-126-3p is overexpressed." (PMID 26244545, 2015). "This suggests that SLC7A5 and ADAM9 are two target genes among others that mediate the tumor suppressive effects of miR-126-3p on growth and migration in thyroid cancer cells." (PMID 26244545, 2015). "In addition, we validated the mRNA expression levels of ADAM9 in thyroid cancer tissues and thyroid cancer cell lines." (PMID 34046406, 2021). "Therefore, RUNDC3A-AS1 might enhance ADAM9 expression by sequestering the miR-182-5p in thyroid cancer." (PMID 34046406, 2021). "Therefore, the RUNDC3A-AS1/miR-182-5p/ADAM9 axis may be a potential therapeutic target for the treatment of thyroid cancer metastasis." (PMID 34046406, 2021). "Therefore, the RUNDC3A-AS1/miR-182-5p/ADAM9 axis may serve as novel biomarkers or potential targets for the treatment of thyroid cancer metastasis." (PMID 34046406, 2021). "We found that miR-126-3p overexpression significantly decreased luciferase activity as compared to the negative control, suggesting that miR-126-3p directly targets the 3′-UTR region of ADAM9 and SLC7A5 in thyroid cancer cells." (PMID 26244545, 2015).